TLR4 (toll like receptor 4)
Diseases named in the same sentence as TLR4 in open-access papers (continued):
Sharing a sentence is not in itself a finding about the gene and the disease.
tumor (continued). "The in vitro and in vivo experiments indicated that multiple substances functioned as immune adjuvant through binding to TLR4 on DCs, and played a promising role in anti-tumor therapy." (PMID 29029545, 2017). "As previously shown, Prx1 interaction with TLR4 on CaP cells promoted prostate cancer growth through chronic activation of tumor angiogenesis." (PMID 29029545, 2017). "TLR4 is expressed not only on tumor cells but also on stromal cells and immune cells that play vital role in antitumor in tumor microenvironment." (PMID 29029545, 2017). "HMGB1 also improves tumor antigen presentation by binding to Toll-like receptor 4 (TLR4) on DCs and preventing the accelerated degradation of antigens within DCs." (PMID 28344743, 2017). "In gene expression arrays, the overexpression of TLR4 in tumor cells correlated with gene expression of ATF-3, IL-6, CDH13, CXCL-1 and TFPI." (PMID 28982115, 2017). "Accumulating evidences demonstrated that the activation of TLR4 in tumor microenvironment can not only boost the anti-tumor immunity but also give rise to immune surveillance and tumor progression." (PMID 29029545, 2017). "Multivariate analysis showed that expression level of TLR4, tumor size, and SUVmax were independent prognostic factors for OS, and TLR4 expression level and SUVmax were independent prognostic factors for DFS (all P < 0.05)." (PMID 28484456, 2017). "Accordingly, neutralizing monoclonal antibody of HMGB1 should incorporate the fact that HMGB1/TLR4 signaling modulates inflammatory responses while HMGB1/RAGE signaling promotes tumor growth and metastasis." (PMID 28969092, 2017). "On the basis of these observations we propose that tumor-released extracellular Hsp70/90 induce muscle wasting primarily by activating the TLR4-p38β MAPK-C/EBPβ catabolic signaling pathway." (PMID 28928431, 2017). "Since tumor cells also express TLR4, TLR4-induced uncontrolled production of immunosuppressive cytokines has been suggested to contribute to the tumor progression." (PMID 28769820, 2017). "Since these individual genes have all been described in cancer models and tissue, we reason their dependence on TLR4 expression as shown in our study supportive for the suggested role of TLR4 in tumor growth." (PMID 28982115, 2017). "TLR4 were found to be recognized by extracellular HSP70 in the tumor microenvironment, and it plays a positive role in proliferation and migration of tumor cells." (PMID 29029545, 2017). "In view of the “double-edged sword” role of TLR4 activation, from my own perspective, the potential role of TLR4 in tumor microenvironment needs to be further clarified." (PMID 29029545, 2017). "In vivo animal experiments further demonstrated that TLR4-knock-down tumor cells displayed a decreased ability to metastasize compared with the control tumor cells after being induced by sB7-H3." (PMID 27273624, 2016). "In some tumour cells, TLR4 signalling has been shown to be functional and to induce the secretion of soluble immune mediators." (PMID 27090571, 2016). "TLR4 is overexpressed in mouse and human inflammation-associated CRC, and TLR4-deficient mice are strongly protected against colon carcinogenesis, suggesting that TLR4 expression on tumor cells promotes tumor progression directly or indirectly." (PMID 27409669, 2016). "Previous studies suggest that co-expression of TLR4 with its ligand, LPS, induce activation of NF-κB in the tumor microenvironment, and also induce tumor growth and development." (PMID 26675260, 2016). "The results are also consistent with reduced expression of the antiapoptotic genes Birc3, Birc5 and Nos2 in livers from TLR4-/- mice suggesting that TLR4 mediates survival ligands to tumor initiating cells." (PMID 27391331, 2016). "On the basis of these observations that LDR in conjugation with LPS drive M1 re-programming of TAM, we strongly anticipated that TLR4/2 Gy driven retuning of TAM would also impart anti-tumor potential in these MΦ." (PMID 27511884, 2016).
tumor (continued). "In summary, these data highlight that TLR4 signalling is necessary for the cationic polymers to exert their anti-tumour activities." (PMID 27074905, 2016). "TLR4 −/− mice treated with intratumoral synthetic E7 long peptide vaccination did not generate significant antitumor effect against buccal TC-1 tumor to prolong survival compared to the control, untreated mice." (PMID 26949512, 2016). "Although the TLR4 profile varies in different tumor cells, current evidence indicates that the expression of TLR4 and signaling cascade are involved in tumor growth, progression and invasion." (PMID 26675260, 2016). "It has been shown that EOC cells bear TLR4 and MyD88, an adapter coupling TLR4 and that TLR4/MyD88 signaling induces the synthesis of immunosuppressive cytokines and facilitates tumor progression and immune evasion." (PMID 27118139, 2016). "This signaling pathway forms a TLR3/TLR4–NF-κB–HIF-1 loop that is closely associated with hypoxia and inflammation in the tumor and leads to tumor cell survival, proliferation, angiogenesis, and metastasis." (PMID 27191981, 2016). "We found that transfection of TLR4 shRNA reduced TLR4 expression at both mRNA and protein levels, and limited LPS-induced tumor outgrowth." (PMID 27286259, 2016). "TLR4 activation in tumor cells promoted the growth of breast, lung, head and neck, and liver tumors in animal models." (PMID 28116318, 2016). "To elucidate the in vivo relevance of our findings in clinical patients, we detected expressions of TLR4 and miR-21 in tumor tissues and adjacent tissues." (PMID 27286259, 2016). "Collectively, TLR4 expressed in tumor or non-tumor cells within the tumor microenvironment uniformly contributes to HCC development in response to microbial infection." (PMID 27623211, 2016). "In this study, we showed that the innate immune system regulated by TLR4 plays a significant role in eliciting the anti-tumor responses against buccal TC-1 tumor." (PMID 26949512, 2016). "In fact, HMGB1 released following chemotherapy-induced cell death activates DCs via the TLR4-MyD88 axis, which leads to the induction of anti-tumor T-cell immunity." (PMID 27172902, 2016). "A TLR4-active agent that promotes anti-tumor immunity while decreasing inflammatory response would be valuable in cancer therapy." (PMID 27909407, 2016). "The tumor sizes in TLR4-defective mice after CCL-34 treatment are close to those in vehicle-treated group, indicating that TLR4 is the main molecular target of CCL-34." (PMID 26883191, 2016). "We observed that TLR4 was expressed at a high level in cancer tissue compared to normal tissue, and level was dependent on tumor stage." (PMID 26675260, 2016). "To further determine the role of histones and TLR4 in tumor metastasis in vivo, we utilized a murine model for pulmonary metastasis by intravenous injection of mouse Hepa1-6 cells." (PMID 27623211, 2016). "Just as is reported in the previous study, silencing TLR4 signaling in tumor cells resulted in reduced tumor formation." (PMID 27409669, 2016). "These endogenous ligands of TLR4 bind and activate TLR4 on tumor and stromal cells during cancer development and contribute to increased evasion of immune surveillance." (PMID 27223258, 2016). "Protein of tumor tissues was extracted to validate the cross-regulation between TLR4/NF –κB and β-catenin in western blot." (PMID 26760960, 2016). "Buccal tumor-bearing mice with intact TLR4 function and received intratumoror synthetic E7 long peptide vaccination, however, survived significantly longer than TLR4 deficient mice who received the same treatment." (PMID 26949512, 2016). "The expression and activation of TLR4 have been reported on a variety of tumor and stromal cells in the tumor microenvironment." (PMID 27223258, 2016). "It was revealed to induce the activation of the toll-like receptor 4 (TLR4) signaling pathway, which was functionally associated with tumor growth, invasion and chemoresistance." (PMID 27649234, 2016).
tumor (continued). "In a syngeneic bladder cancer cell model, CCL-34 was demonstrated to delay tumor growth via TLR4-dependent activation of immune cells." (PMID 26883191, 2016). "In our previous investigation, CCL-34 treatment suppressed tumor growth and benefited the survival in a TLR4-dependent manner." (PMID 26883191, 2016). "CD40 in conjunction with TLR-4 has been reported in substantially augmenting DCs activity to regress tumor growth and optimally activate T cells." (PMID 27729911, 2016). "Otherwise, it is reported that activation of TLR4 played an important role in the evolution of malignant behavior of tumor, including tumor formation, tumor invasion and distant metastasis." (PMID 26760960, 2016). "In conclusion, LPS-induced TLR4 signaling in CRC affects tumor growth, adhesiveness and metastatic capability." (PMID 27409669, 2016). "TLR4 activation of host macrophages resulted in the production of several different inflammatory cytokines that influenced tumor growth." (PMID 27389279, 2016). "TLR4 controls the tumor antigen processing and is, therefore, indispensable for efficient cross-presentation of tumor cell antigens by DCs." (PMID 26483791, 2015). "The preventive effect is dependent on mice TLR4 and the therapeutic effect is probably dependent only on tumor TLR4." (PMID 25973756, 2015). "Among these functions, it was observed that tumour and virus-infected cells were able to secrete Prxs, which bind to Toll-like receptor 4 (TLR4), linking peroxiredoxin proteins with the immune response." (PMID 26633533, 2015). "HMGB1, combined with its receptors RAGE and TLR4, appears to be an attractive target for treatment of tumour angiogenesis via neutralization by specific antibodies." (PMID 26099505, 2015). "TLR4 is the major receptor that recognizes the DAMPs exposed by tumor cells, which can facilitate intracellular antigen processing and presentation activities." (PMID 26403780, 2015). "Simultaneously, the downregulation of TLR4 in Le-TLR4 xenograft tumors contributed to a remarkable reduction in the tumor weight (P < 0.05)." (PMID 26514586, 2015). "TLR4 binds HMGB1 what prevents tumor antigens digestion and facilitates their trafficking to the dedicated antigen-presenting compartment." (PMID 25801067, 2015). "HMGB1 interaction with a functional TLR4 on DCs is required for an efficient cross-presentation of tumor-antigens to T cells and the priming of a tumor-specific T-cell response." (PMID 26500646, 2015). "Other than mice strains B16 tumor cell line has also been studied extensively in regard to TLR-4 and showed that IFN-γ was the critical factor produced by TLR-4 activated tumor cells in mediating in vitro outgrowths and is enhanced after LPS stimulation." (PMID 25759837, 2015). "In vivo immunoregulatory and anti-tumor activities of PSP were examined in B10 (TLR4+/+) or ScCr (TLR4−/−) mice inoculated with Ehrlich’s ascites carcinoma (EAC) cells." (PMID 26032186, 2015). "In the case of oral HNSCC, TLR4 stimulation with LPS has been shown to confer resistance to tumor lysis by natural killer cells and promote survival." (PMID 25846753, 2015). "We demonstrate that stimulating B16 cells with BLS in vitro-before its inoculation- significantly augments survival and that this effect is abolished when tumor cells are pretreated with TLR4/MD2 monoclonal antibody." (PMID 25973756, 2015). "More recently, microbial LPS translocation and signaling through TLR4 have also been shown to account for the enhanced anti-self tumor antigen responses observed after irradiation and adoptive CD8+ T cell transfer in mouse models." (PMID 26075613, 2015). "As our previous studies indicated that SREC-I required intact Toll-like receptor 4 (TLR4) expression for its functions in tumor immunity, we examined potential interactions between these two receptors." (PMID 25836976, 2015).
tumor (continued). "To identify which receptor was responsible for HMGB1 binding, we pretreated live DU145 tumor cells with anti-TLR4, anti-RAGE or the combination of both antibodies for 30 min prior to addition of recombinant HMGB1." (PMID 26469759, 2015). "Addition of anti-HMBG1 to the supernatant or pretreatment of newly-plated DU145 tumor cells with anti-TLR4 or anti-RAGE markedly abrogated sCLU induction and protective effect of the supernatant." (PMID 26469759, 2015). "Prophylactic treatment with the TLR4 and TLR9 agonist complex triggered anti-metastatic immunity and impaired tumor metastasis by inducing the autophagy-associated death of melanoma cells via IFN-γ/STAT1 activation." (PMID 25743109, 2015). "It was previously reported that in vitro stimulation of B16 cells with LPS reduces subsequent tumor growth in mice and that this effect is dependent on tumor TLR4." (PMID 25973756, 2015). "From the results, we found that the mRNA and protein levels of TLR4, TRAF6, NF-κB and AP-1 were significantly upregulated by PSP as well as LPS in spleens of B10 (TLR4+/+) tumor-bearing mice." (PMID 26032186, 2015). "Compared to the NS group and control group, the Le-TLR4 group showed a significant reduction in the tumor volume (P < 0.05)." (PMID 26514586, 2015). "Maccioni ́s group reported that LPS signaling via TLR4 on tumor cells in vitro triggers the secretion of IFN-γ by tumor-infiltrating lymphocytes, and the secretion of IFN-β by tumor cells, modifying tumor outgrowth in vivo." (PMID 25973756, 2015). "Given that the importance of TLR4 signaling in tumor development and growth, in this study we aimed to explore the effects of TLR4 activation on the growth and survival of HBV-related HCC cells and to examine the molecular mechanisms involved." (PMID 26514586, 2015). "Tumor cells deficient in HMGB1 exhibit compromised capacity to induce ICD and anti-tumor immune responses, however, TLR4 agonists rescued the chemotherapy-induced anti-tumor immune responses." (PMID 26486085, 2015). "To evaluate the possible impact of LPS contamination on the induced anti-tumor immune responses, we performed prophylactic immunization experiments with TLR4 knockout mice (C57BL10/ScCr)." (PMID 26390407, 2015). "Altogether, the results presented in this work show that the response induced by BLS via TLR4 in vaccinated mice is able to protect them-at least in some extent- against tumor growth." (PMID 25973756, 2015). "Twenty five days after inoculation, the mean weights of tumors in B10 (TLR4+/+) tumor-bearing mice that received PSP and ADM treatment were significantly decreased compared with those in the saline group (all p < 0.05)." (PMID 26032186, 2015). "This action was due to HMGB1 binding to TLR4 or RAGE, as pretreatment of the supernatant with anti-HMGB1 or pretreatment of the live tumor cells with anti-TLR4/RAGE markedly inhibited sCLU induction." (PMID 26469759, 2015). "In an alternative approach, plasma membrane of tumor cells has been extracted and coated onto polymeric nanoparticle cores along with the TLR4 agonist MPLA as a tumor cell-mimicking cancer vaccine." (PMID 26350600, 2015). "HMGB1 in turn activated TLR4 and elevated the pro-tumor factors IL-6 and miR-21, together with other important factors like MMP9 and miR-155, to induce carcinogenesis." (PMID 25923834, 2015). "Another finding supporting the direct effect of BLS on tumor cells TLR4, is that the therapeutic effect correlates with the presence of TLR4 at the tumor ́s surface." (PMID 25973756, 2015). "The effectiveness of the treatment with BLS prior to tumor cell inoculation depends on mice TLR4 signaling." (PMID 25973756, 2015). "Matched normal tissues derived from colon remote from tumor showed trends toward lower TLR4 expression in CRC epithelium compared to normal epithelium (coef = 0.68, p = 0.18)." (PMID 24887394, 2014).
tumor (continued). "These lentivirus particles reduce IgG expression by directly injecting into the tumor body and infecting tumor cells, which will lead to down-regulation of TLR4 expression according to our results." (PMID 25179302, 2014). "Analogous to CACs, we have found an association between TLR4 expression in sporadic CRC and the progression of neoplasia, stage, DFS, and MSS." (PMID 24887394, 2014). "The epithelium of 11/174 (6.32%) of CRCs was positive for TLR4 expression; 6/174 (3.45%) of tumor epithelia were strongly positive." (PMID 24887394, 2014). "It was shown that TLR4 expressed on DCs was required for the cross presentation of tumor antigens and the promotion of tumor specific cytotoxic T-cell responses." (PMID 24904578, 2014). "Both TLR3 and TLR5 are also pro-tumorogenic with their signals mediating tumor invasion and metastasis by enhancing cell migration, but, like TLR4, also have an anti-cancer effect in some situations." (PMID 25309546, 2014). "RT-PCR and immunohistochemistry showed that TLR4 was expressed in tumor tissue, however, normal breast tissue hardly expressed TLR4." (PMID 25299052, 2014). "Paclitaxel, a known TLR4 ligand, leads to activation of TLR4/MyD88-dependent pathway that mediates chemoresistance and tumor progression in epithelial ovarian carcinoma (EOC)." (PMID 24452475, 2014). "OM-174 is a triacyl lipid A analog that activates TLR4 and culminates in tumor growth regression by increasing the IFN-γ production This is well-tolerated at biological concentrations with strong antitumor effects (NCT01800812)." (PMID 25076949, 2014). "35.6% of CRCs demonstrate high levels of TLR4 protein in the tumor stroma, while 3.45% have high levels in the tumor epithelium." (PMID 24887394, 2014). "They determined that TLR4 stimulation by LPS in tumor cells increased production of numerous soluble factors, such as IL-6, and ultimately inhibited the ability of CTLs to recognize and kill the cancer cells." (PMID 25101083, 2014). "The suppressed release of IL-8 from LPS stimulated PMN from healthy donors cultured in FaDu supernatants indicates that the tumor cells release mediators that inhibit the TLR4 signaling pathway for IL-8 secretion." (PMID 24466243, 2014). "It has been demonstrated that there is a strong association between TLR3, TLR4 and TLR9 expression and tumor aggressiveness and poor prognosis in HCC." (PMID 24932259, 2014). "During chemotherapy or radiotherapy, DCs require signaling through TLR4 and its adaptor MyD88 for efficient processing and cross-presentation of antigen from dying tumor cells." (PMID 25328756, 2014). "Further, the authors demonstrated that inhibition of TLR4 signaling in tumor cells significantly increased survival in animal studies." (PMID 25101083, 2014). "This is the first demonstration of anti-tumor activity of Immunomax® against occult micrometastatic tumor and the first in vitro demonstration that this immunostimulator is a TLR-4 agonist directly activating DC and NK cells co-operation." (PMID 25432242, 2014). "Although the response of DCs to heat-killed necrotic tumor cells was shown to be dependent on TLR4 expression, we observed that the effects on Th polarization are different from that of LPS." (PMID 24802102, 2014). "Using real-time PCR, we confirmed that tumor tissues expressed TLR4 more than normal breast tissues did." (PMID 25299052, 2014). "The expression of two microRNAs known to regulate the TLR4/MyD88 pathway was also evaluated in a subset of malignant tumour samples to explore their role as epigenetic modulators of this pathway." (PMID 24977712, 2014). "The TLR4 staining score in the tumor epithelium was classified by tumor grade: well-differentiated = 0.57, moderately-differentiated = 0.84, poorly-differentiated = 0.00, or undifferentiated = 0.23 (ANOVA comparing all four categories, p = 9.99 × 10−9)." (PMID 24887394, 2014).